UBE2J1 (ubiquitin conjugating enzyme E2 J1)
Description:
Catalyzes the covalent attachment of ubiquitin to other proteins. Functions in the selective degradation of misfolded membrane proteins from the endoplasmic reticulum (ERAD) and is essential for cells to recover from ER stress. Plays a role in MAPKAPK2-dependent translational control of TNF synthesis. Also acts as a platform for perinuclear positioning of the endosomal system by mediating ubiquitination of SQSTM1 through interaction with the E3 ubiquitin-protein ligase RNF26. Plays a role in male fecundity through the interaction with the E3 ubiquitin-protein ligase RNF133. (Microbial infection) Promotes Dengue virus RNA replication by negatively regulating IFN-beta signaling and mediating 'Lys-48'-linked ubiquitination on IRF3.
Synonyms: NCUBE-1; NCUBE1; CGI-76; HSPC153; HSPC205; UBC6; HSU93243; UBC6E; Ubc6p
Tractability: Antibody: UniProt predicts a signal peptide or a membrane-spanning region. PROTAC: UniProt records ubiquitination sites on it; ubiquitination databases record sites on it; its protein half-life has been measured.
Gene: Protein-coding gene on chromosome 6 (89,326,608 to 89,352,902, reverse strand). Ensembl gene ENSG00000198833.
Subcellular location: Endoplasmic reticulum membrane
Pathways (Reactome):
Immune System: Antigen processing: Ubiquitination & Proteasome degradation
Gene Ontology:
Molecular function: protein binding; ubiquitin conjugating enzyme activity; ubiquitin protein ligase binding
Biological process: ERAD pathway; negative regulation of retrograde protein transport, ER to cytosol; protein N-linked glycosylation; protein polyubiquitination; protein ubiquitination
Cellular component: endoplasmic reticulum membrane; Hrd1p ubiquitin ligase complex
Genetic constraint (gnomAD): Loss-of-function variants: 15 observed, 34.89 expected, observed/expected ratio (o/e) 0.43, 90% interval 0.29 to 0.66. The upper end of that interval is the gene's LOEUF score, 0.66, which puts it in group 2 of 6, group 1 being the genes least tolerant of losing a copy. Missense variants: 269 observed, 363.37 expected, observed/expected ratio (o/e) 0.74, 90% interval 0.67 to 0.82. Synonymous variants: 115 observed, 127.82 expected, observed/expected ratio (o/e) 0.9, 90% interval 0.77 to 1.05.
Homologues: Orthologues: macaque UBE2J1 (98% identical), dog UBE2J1 (96% identical), pig UBE2J1 (95% identical), rabbit UBE2J1 (94% identical), mouse Ube2j1 (92% identical), rat Ube2j1 (92% identical), guinea pig Ube2j1 (92% identical), tropical clawed frog ube2j1 (70% identical), zebrafish ube2j1 (64% identical), Caenorhabditis elegans ubc-6 (42% identical). Paralogues in human: UBE2J2 (27% identical), UBE2N (18% identical), CDC34 (17% identical), UBE2K (16% identical), UBE2NL (16% identical), UBE2R2 (15% identical), UBE2B (14% identical), UBE2F (14% identical), UBE2C (14% identical), UBE2A (14% identical), UBE2T (14% identical), UBE2Z (14% identical), and 12 more.
Diseases named in the same sentence as UBE2J1 in open-access papers:
UBE2J1 is named in the same sentence as 13 diseases in open-access papers, as found by Europe PMC text mining. Sharing a sentence is not in itself a finding about the gene and the disease. The quoted sentences say what the papers report.
colorectal cancer (3 papers, 2023 to 2025). A primary or metastatic malignant neoplasm that affects the colon or rectum. "Another study has confirmed that UBE2J1 inhibits the progression of colorectal cancer by enhancing the ubiquitination and degradation of RPS3." (PMID 38656363, 2024). "Here, we identified that UBE2J1 is downregulated in colorectal cancer (CRC) tissues and cell lines which are mediated by DNA hypermethylation of its promoter, and decreased UBE2J1 is associated with poor prognosis." (PMID 36567344, 2023). "Moreover, recent research has indicated that UBE2J1 can act as a tumor suppressor, inhibiting the proliferation and metastasis of colorectal cancer." (PMID 40697329, 2025). "Methylation of UBE2J1 was detected in 71.4% (20/28) of primary colorectal cancers, and no methylation was found in all 28 cases of non-cancerous colorectal tissue samples." (PMID 36567344, 2023).
endometrial cancer (2 papers, 2023). Primary or metastatic malignant neoplasm involving the endometrium (mucous membrane that lines the endometrial cavity). "Recently, UBE2J1 is also found to participate in medulloblastoma development, and facilitate endometrial cancer progression." (PMID 36567344, 2023). "UBE2J1 was reported to be dysregulated in endometrial cancer (EC)." (PMID 36852267, 2023).
prostate carcinoma (2 papers, 2023 to 2024). A carcinoma that arises from epithelial cells of the prostate gland. "Up to now, it has been documented that prostate cancer patients with high UBE2J1 expression share a relatively poor prognosis." (PMID 36567344, 2023). "We hypothesized that high-grade prostate cancer (PCa) patients, particularly those with Gleason scores of 9–10, who are more prone to develop resistance, would exhibit reduced expression of UBE2J1 compared to patients with low-grade tumors (Gleason scores 6–8)." (PMID 38030789, 2024).
hepatocellular carcinoma (1 paper, 2023). A malignant tumor that arises from hepatocytes. "In addition, the ectopic expression of UBE2J1 in hepatocellular carcinoma (HCC) was reported to induce poor survival in patients with HCC." (PMID 36852267, 2023).
Infertility (1 paper, 2025). "Nevertheless, as RNF133 deficiency only leads to subfertility while UBE2J1 deficiency leads to total infertility, additional factors may play a role in this process." (PMID 40412517, 2025).
male infertility (1 paper, 2025). The inability of the male to effect fertilization of an ovum after a specified period of unprotected intercourse. "The loss of ubiquitin conjugating enzyme E2 J1 (UBE2J1), a key E2 enzyme in the ERAD pathway, causes male infertility and defective ER and cytoplasm removal during spermiogenesis in mice." (PMID 40412517, 2025).
myeloma (1 paper, 2013). "Interestingly, the list includes the gene SLC31A2 a membrane pump involved in resistance to alkylating drugs; FBXW7, USP6, UBE2J1 and Wnt-5a involved in ubiquitin proteasome pathways known to affect myeloma biology." (PMID 24376673, 2013).
virus infection (1 paper, 2018). "We next evaluated whether UBE2J1 influence the innate immune responses to viral infection." (PMID 30157886, 2018).
cancer (8 papers, 2013 to 2025). A tumor composed of atypical neoplastic, often pleomorphic cells that invade other tissues. "To deepen our understanding of the role of UBE2J1-loss in antiandrogen resistance, we examined two metastatic Castration Resistant Prostate Cancer (mCRPC) patient cohorts: the Stand Up to Cancer (SU2C) and Alumkal 2020 cohorts." (PMID 38030789, 2024). "Nevertheless, rare research showed that UBE2J1 as a ubiquitin-conjugating enzyme is implicated in cancer development and progression." (PMID 36567344, 2023). "Previous studies have revealed that UBE2J1 facilitates malignant phenotypes of many human cancers and is closely associated with poor overall survival and unfavorable prognosis of patients." (PMID 36852267, 2023). "However, there is a deficiency of studies on UBE2J1 functioning as a ubiquitin-conjugating enzyme in cancer." (PMID 36567344, 2023). "However, the underlying mechanisms of UBE2J1 as a ubiquitin-conjugating enzyme participating in cancer development and progression remain largely unknown." (PMID 36567344, 2023). "Despite these findings, the role of UBE2J1 as a ubiquitin-conjugating enzyme in cancer remains insufficiently studied." (PMID 40697329, 2025). "We also analyzed the protein levels of cell apoptosis markers in cancer cells after the co-transfection of sh-UBE2J1 and pcDNA3.1/MDM2 to validate the interaction between UBE2J1 and MDM2." (PMID 36852267, 2023). "Emerging evidence has demonstrated that ubiquitin conjugating enzyme E2 J1 (UBE2J1) exerts pivotal function in many cancers." (PMID 36852267, 2023). "Ubiquitin conjugating enzyme E2 J1 (UBE2J1) has been reported to exert biological functions on several cancers." (PMID 36852267, 2023). "UBE2F and UBE2J1 are ubiquitin conjugating enzymes that are involved in inflammation and in metastasis development in many cancers." (PMID 30866419, 2019). "Moreover, emerging evidence has shown that UBE2J1 is involved in gene modulation in human cancers through different signaling pathways." (PMID 36852267, 2023).
tumor (6 papers, 2017 to 2025). "To validate this hypothesis, we analyzed patient data from the TCGA cohort segregated by tumor grade (Gleason score) and found a significant reduction in UBE2J1 expression in high-grade PCa patients compared to their low-grade counterparts, affirming the clinical relevance of UBE2J1-loss." (PMID 38030789, 2024). "Immunohistochemistry (IHC) staining of these tumor samples showed a significant reduction of UBE2J1, accompanied by an increase in AR and AR target NKX3.1 proteins, in PCa compared to matched benign prostate tissue." (PMID 38030789, 2024). "Xenograft tumor models showed that cells with depleted UBE2J1 had a promoting tumor growth, which was reflected in more tumor volume and weight than that in control, while overexpression of UBE2J1 exhibited an opposite effect." (PMID 36567344, 2023). "We found that down regulation of each of 4 genes, i.e., SMAP1 (6q13), ZNF292 (6q14), HMGN3 (6q14), and UBE2J1 (6q15) significantly increased cell growth over background in colony formation assays performed in duplicate (P ≤ 0.0139), thus supporting a tumor suppressive role for these four genes." (PMID 29312579, 2017). "TRIM69, Ube2j1, ZBTB4, and SKP2 show the most pronounced effects on the immune microenvironment of the tumor." (PMID 40697329, 2025). "Moreover, the differential expression of TRIM69, Ube2j1, ZBTB4, and SKP2 likely serves a critical function in modulating tumor immune infiltration." (PMID 40697329, 2025).
UBE2J1 also shares sentences with these, for which no sentence is quoted: infection (2 papers); medulloblastoma (1); schizophrenia (1).